HCRT (hypocretin neuropeptide precursor)
Description:
Neuropeptides that play a significant role in the regulation of food intake and sleep-wakefulness, possibly by coordinating the complex behavioral and physiologic responses of these complementary homeostatic functions. A broader role in the homeostatic regulation of energy metabolism, autonomic function, hormonal balance and the regulation of body fluids, is also suggested. [Orexin-A]: Binds to orexin receptors HCRTR1/OX1R and HCRTR2/OX2R with a high affinity (By similarity). Stimulates food intake (By similarity). Modulates pituitary luteinizing hormone secretion in an ovarian steroid-dependent manner (By similarity). [Orexin-B]: Binds to orexin receptor HCRTR2/OX2R only (By similarity). Stimulates food intake (By similarity). Modulates pituitary luteinizing hormone secretion in an ovarian steroid-dependent manner (By similarity).
Synonyms: OX; PPOX; NRCLP1
Tractability: Small molecule: a structure with a bound ligand is known. Antibody: its Gene Ontology location is reachable by antibodies, with high confidence; UniProt predicts a signal peptide or a membrane-spanning region.
Gene: Protein-coding gene on chromosome 17 (42,184,060 to 42,185,452, reverse strand). Ensembl gene ENSG00000161610.
Subcellular location: Rough endoplasmic reticulum; Cytoplasmic vesicle; Synapse
Pathways (Reactome):
Signal Transduction: G alpha (q) signalling events; Orexin and neuropeptides FF and QRFP bind to their respective receptors
Gene Ontology:
Molecular function: neuropeptide hormone activity; type 1 orexin receptor binding; type 2 orexin receptor binding
Biological process: chemical synaptic transmission; eating behavior; positive regulation of cold-induced thermogenesis; positive regulation of transmission of nerve impulse; regulation of neurotransmitter secretion; response to starvation; sleep; temperature homeostasis; behavioral response to ethanol; drinking behavior; excitatory postsynaptic potential; feeding behavior; negative regulation of DNA replication; negative regulation of potassium ion transport; negative regulation of transmission of nerve impulse; neuropeptide signaling pathway; phospholipase C-activating G protein-coupled receptor signaling pathway; positive regulation of calcium ion transport; positive regulation of cytosolic calcium ion concentration; response to alcohol; response to peptide
Cellular component: cytoplasmic vesicle; extracellular region; perinuclear region of cytoplasm; rough endoplasmic reticulum; synapse; synaptic vesicle; neuronal dense core vesicle lumen; postsynapse; secretory granule
Genetic constraint (gnomAD): Loss-of-function variants: 6 observed, 5.29 expected, observed/expected ratio (o/e) 1.13, 90% interval 0.61 to 1.85. That is too few expected variants to judge how well the gene tolerates losing a copy. Missense variants: 207 observed, 132.41 expected, observed/expected ratio (o/e) 1.56, 90% interval 1.39 to 1.75. Synonymous variants: 114 observed, 68.28 expected, observed/expected ratio (o/e) 1.67, 90% interval 1.43 to 1.91.
Homologues: Orthologues: chimpanzee HCRT (99% identical), macaque HCRT (95% identical), pig HCRT (90% identical), rabbit HCRT (90% identical), dog HCRT (89% identical), rat Hcrt (83% identical), mouse Hcrt (82% identical), guinea pig HCRT (73% identical), tropical clawed frog hcrt (48% identical), zebrafish hcrt (31% identical).
Diseases named in the same sentence as HCRT in open-access papers:
HCRT is named in the same sentence as 150 diseases in open-access papers, as found by Europe PMC text mining. Sharing a sentence is not in itself a finding about the gene and the disease. The quoted sentences say what the papers report.
narcolepsy (80 papers, 2009 to 2026). A sleep disorder characterized by a tendency for excessive sleepiness during the day which occurs even after adequate sleep in the nighttime. "The distinctive pathologies associated with the disruption of HCRT neurons are narcolepsy and cataplexy, which are caused by the loss of hypocretin neurons that produce HCRT." (PMID 39796111, 2024). "One patient with an early-onset narcolepsy with cataplexy has been reported to have a heterozygous mutation in the HCRT gene (hypocretin, also known as orexin) on chromosome 17q21.2." (PMID 39484177, 2023). "Dysfunction of the HCRT gene, either through genetic mutations or autoimmune-mediated destruction of the orexinergic neurons, has been implicated in the development of narcolepsy and other symptoms related to sleep fragmentation." (PMID 39484177, 2023). "All these observations led to the assumption of narcolepsy being merely due to the selective HCRT-neuronal cell disruption and loss." (PMID 35445831, 2022). "A correlation analysis with known genes associated with these disorders(LRRK2, HLA-DQB1, and HCRT) was used to query microarray data corresponding to brain regions known to be involved in PD and narcolepsy." (PMID 34745571, 2020). "Even though it is known that the loss of the neuropeptide orexin (hypocretin, HCRT) system causes narcolepsy with cataplexy, the entire brain circuitry responsible for the presentation of all narcoleptic symptoms is not fully understood." (PMID 31411561, 2019). "The dramatic effect of the complete loss of hypocretinergic signaling demonstrated in narcolepsy with cataplexy has given rise to a theory of a switching or gating function of HCRT in neuronal, including trigeminal, processing." (PMID 26289164, 2015). "Deficient HCRT neurotransmission is sufficient to produce narcolepsy, as animal models with dysregulated HCRT transmission exhibit a narcolepsy-like phenotype." (PMID 19158946, 2009). "In humans, loss of HCRT neurons is associated with the sleep disorder narcolepsy and inappropriate triggering of REM sleep." (PMID 19623260, 2009). "There are two HCRT receptors (hypocretin-1 and 2 receptors) and in canine narcolepsy, the REM sleep abnormality results from a mutation in the HCRT-2 receptor." (PMID 19623260, 2009). "Moreover, there are cases of false diagnoses of schizophrenia in patients with narcolepsy caused by HCRT deficiency, including those due to possible hypnagogic hallucinations in such patients." (PMID 39796111, 2024). "If this overexpression is part of the pathogenesis of narcolepsy or a compensatory mechanism due to the HCRT-neuronal loss remains unclear." (PMID 35445831, 2022). "HCRT deficiency is known to cause the life-long disease narcolepsy with cataplexy." (PMID 30341359, 2018). "Loss of HCRT signaling by disruption of Hcrt, both Hcrtr1 and Hcrtr2 genes, or ablation of HCRT-producing cells, profoundly alters behavioral state regulation, and closely phenocopies narcolepsy symptomatology." (PMID 30341359, 2018). "In the year 2000, a selective reduction of HCRT-neurons (and axons) in the lateral hypothalamus has been found in human narcolepsy." (PMID 35445831, 2022). "Animal studies established that the HCRT system is critical in sustaining the normal waking state and its genetic defects lead to narcolepsy phenotypes in mice and dogs." (PMID 33247179, 2020). "Our analysis of in vivo expansion of HCRT-reactive TRAJ24+ cells opens an avenue for further investigation of the autoimmune contribution to narcolepsy development." (PMID 31748512, 2019). "The assumption that narcolepsy is related to the hypocretin system function (HCRT-1 and -2, also known as orexin-A and -B, respectively) is supported by several lines of evidence." (PMID 24736646, 2014). "Experiments on the HCRT/ataxin-3 narcolepsy mouse model demonstrated that intracerebroventricular (ICV) injections of HCRT-1 can compensate for HCRT cell loss and reverse most of the narcolepsy symptoms including cataplexy." (PMID 24736646, 2014).
narcolepsy (continued). "Studies in animal models of narcolepsy have shown the neurophysiological role of the HCRT system in the development of this disease." (PMID 24736646, 2014). "Of notable interest is a transgenic mouse model where the HCRT promoter drives a form of ataxin-3 containing a large polyglutamine repeat, resulting in HCRT cell death and a narcolepsy-like phenotype at 2–3 weeks of age." (PMID 19158946, 2009). "This colocalization was also seen in some of the few remaining HCRT neurons in brains from narcolepsy patients." (PMID 19158946, 2009). "The overexpression of HCRT in D. rerio larvae causes wakefulness, whereas physical damage to HCRT cells or mutation of the receptor (HCRTR−/−) leads to fragmentation of sleep in fish, which is observed in patients with narcolepsy." (PMID 39796111, 2024). "If the HCRT gene can be reactivated, narcolepsy can be treated or even cured." (PMID 38725645, 2024). "In this study, we generated a zebrafish P2Y11 mutant using CRISPR/Cas9 genome editing and demonstrated that the P2Y11 mutant replicated the narcolepsy-like features including reduced HCRT expression and excessive daytime sleepiness, suggesting that P2Y11 is essential for HCRT expression." (PMID 38771396, 2024). "Notably, a new report has recently challenged this model showing that HCRT-neurons are still present in the brain of animal models and narcolepsy patients, but HCRT gene is epigenetically silenced in these neurons." (PMID 35445831, 2022). "A partial loss of HCRT-neurons leads instead to EDS (narcolepsy) without cataplexy and with normal CSF HCRT levels." (PMID 35445831, 2022). "Earlier observations that acute administration of HCRT increases brain Aβ and that HCRT antagonism lessened amyloid plaque accumulation in a mouse model of AD prompted assessment of the prevalence of AD in humans with narcolepsy." (PMID 36275002, 2022). "Cataplexy is the pathognomonic symptom of HCRT deficiency, and HcrtKO/KO mice express more REMS in dark periods, while they show profoundly diminished REMS latencies following prolonged wakefulness, as do human narcolepsy patients." (PMID 33247179, 2020). "HCRT dysregulation leads to pathological conditions like narcolepsy and sleep apnea." (PMID 28367113, 2017). "Although hypothesized in animal studies, a temporal and causal association between HCRT deficiency and NT1 onsethas been reported in only two patients with narcolepsy." (PMID 28364477, 2017). "It has, however, become clear that the phenotype exhibited in narcolepsy with cataplexy, brought about by a complete loss of hypocretinergic signaling, does not reveal all of HCRT’s functions." (PMID 26289164, 2015). "Previously used groupings of CSF intervals for HCRT-1 concentrations (low (≤110 pg/ml), intermediate (>110 ≤ 200 pg/ml), and normal (>200 pg/ml)) were not strictly applied in this sample as these are most relevant in the diagnosis of narcolepsy." (PMID 26289164, 2015). "This striking result suggests that if this precise neuroanatomical region had been targeted, it would have been possible to discover the central feature of narcolepsy -HCRT deficiency- without a preconceived hypothesis." (PMID 19158946, 2009). "Mutant larvae exhibited excessive daytime sleepiness and a lower level of HCRT expression, implying that zebrafish P2RY11 mutants convincingly model human narcolepsy." (PMID 38771396, 2024). "Nevertheless, the identification of sequence similarity of HCRTR2 and HCRT itself with nucleoprotein (NP) and HA of 2009 H1N1, respectively, strongly suggested a molecular mimicry mechanism in the pathophysiology of narcolepsy." (PMID 35445831, 2022). "Here, we found that definite cataplexy, the pathognomonic symptom of narcolepsy, may occurin the absence of CSF HCRT-1 deficiency (patients 1, 2, 4, and 6), even in the context ofthe HLA DQB1*06:02 genotype and when narcolepsy is not secondary to another medicalcondition." (PMID 28364477, 2017).
narcolepsy (continued). "Thus, the findings that HCRT neurons are lost in narcolepsy lead to the hypothesis that these neurons might be replaced and raise the question whether the transplantation of HCRT neurons into LH of lesioned rats would improve the sleep disturbances in a narcoleptic experimental model." (PMID 24736646, 2014). "For example, lack of HCRT or its receptors has been reported to lead to narcolepsy along with cataplexy in animal models and humans." (PMID 40158131, 2025). "This problem was overcome by Mieda and co-workers in a mouse model designed to drive non-regulated over-expression of the HCRT gene in mice lacking HCRT neurons, resulting in a rescue from narcolepsy symptoms." (PMID 24736646, 2014). "So far this approach has shown promising results in mice, as Liu and colleagues demonstrated a rescue from narcolepsy symptoms through non-specific overexpression of HCRT by non-HCRT cells in the hypothalamus in two different animal models of narcolepsy." (PMID 24736646, 2014).
Cataplexy (49 papers, 2010 to 2026). A sudden and transient episode of bilateral loss of muscle tone, often triggered by emotions. "A 3rd theta-dominated state is cataplexy, narcolepsy pathognomonic symptom and HCRT deficiency signature." (PMID 38123729, 2024). "However, in HCRT-deficient patients with narcolepsy-cataplexy, muscle sympathetic nerve activity is not reduced during rested wakefulness compared with controls and significantly increases during cataplexy." (PMID 23056568, 2012). "SNP (rs2305795) of the P2RY11 gene is found to be related to narcolepsy with cataplexy (Narcolepsy type 1, NT1), which is an immune-related disease characterized by a significant loss of HCRT (hypocretin neuropeptide precursor; also known as orexin) neurons." (PMID 38771396, 2024). "The essential role of HCRT neurotransmission in the normal regulation of vigilance states, specifically waking and cataplexy, is well-established." (PMID 33247179, 2020). "Baseline PSG-MSLT and CSF HCRT-1 measurements were performed at referral (20months after cataplexy onset) and showed normal mean sleep latency (12 min) without anySOREMP and intermediate CSF HCRT-1 level (163 pg/mL)." (PMID 28364477, 2017). "Optogenetic excitation of DAVTA terminals within BLA of narcoleptic mice exposed to chocolate induced DA transients and cataplexy, while WT mice experienced a much smaller DA release, suggesting HCRT may inhibit DA release." (PMID 38123729, 2024). "But for patients without cataplexy, decreased CSF levels of HCRT are not as predictive, even in combination with the genetic marker DBQ." (PMID 25873764, 2015). "Moreover, the lack of HCRT neurons in patients with narcolepsy-cataplexy or in mouse models entails substantial consequences on the wake-sleep behavior, which include fragmentation of wakefulness, reduced latency of REMS episodes, and cataplexy." (PMID 23056568, 2012).
Obesity (32 papers, 2011 to 2025). Accumulation of substantial excess body fat. "Consistently, decreased Hcrt expression has been associated with weight gain in rodent models of obesity, in agreement with the documented long term catabolic action of HCRT." (PMID 37445827, 2023). "QTL for NVD was homologous with HSA 17q21 regions which contained many obesity candidate genes including PPY, PON1 and 2, GAST, PNMT, STAT3 and HCRT." (PMID 23977060, 2013).
narcolepsy type 1 (27 papers, 2009 to 2026). "Adding to the controversy are two conflicting papers describing measurements of plasma HCRT-1 levels in narcolepsy type 1 (NT1) patients." (PMID 33977264, 2021). "Recent data also indicate that sleep-dependent changes in blood pressure are blunted in mouse models and narcolepsy-cataplexy patients lacking HCRT neurons, suggesting that HCRT neurons play a role in sleep-related cardiovascular control." (PMID 23056568, 2012).
Anxiety (20 papers, 2017 to 2026). Intense feelings of nervousness, tension, or panic often arise in response to interpersonal stresses. "HCRT is closely associated with wakefulness and narcolepsy because of its role in the regulation of vigilance and arousal states, so it raises the question of if the BST-HCRT-LH pathway can help explain the sleep disruptions commonly associated with anxiety." (PMID 33867924, 2021). "Like MCH, HCRT stimulates the release of DA; mediates the reinforcement of drug-seeking behavior for all major drug classes including alcohol, nicotine and cocaine; and is positively associated with the development of emotional disorders such as anxiety and depression." (PMID 40806293, 2025). "It is possible that upregulation of CRH neurons in the BST and subsequent activation of HCRT-LH neurons may therefore contribute to the increased arousal states associated with anxiety and other altered mood states, as well as contribute to the role of the BST in regulating addiction." (PMID 33867924, 2021).
Alzheimer disease (14 papers, 2013 to 2025). A progressive, neurodegenerative disease characterized by loss of function and death of nerve cells in several areas of the brain leading to loss of cognitive function such as memory and language. "Moreover, decreases in CSF levels of HCRT are also associated now, being associated with other diseases, including dementia with Lewy Body and Alzheimer's disease and Kleine-Levin syndrome." (PMID 25873764, 2015).
insomnia (14 papers, 2014 to 2025). A sleep disorder characterized by difficulty in falling asleep and/or remaining asleep. "The human Hypocretin Neuropeptide Precursor (HCRT) and zebrafish homolog hcrt decrease the arousal threshold when overexpressed, resulting in insomnia in humans and increased locomotion in zebrafish." (PMID 35813062, 2022).
migraine (10 papers, 2012 to 2025). "Polymorphisms in the serotonin transporter gene (SLC6A4) and the hypocretin receptor 1 gene (HCRTR1) may be risk factors for migraine development due to their ability to affect serotonin and hypocretin-1 (HCRT-1) concentrations." (PMID 29922128, 2018). "The strict relation between 5-HT and HCRT-1 may be altered in migraine patients due to different genetic variants of 5-HTTLPR and HCRTR1 G1222A or *G29A." (PMID 29922128, 2018). "Higher HCRT-1 concentration was characterized by shorter migraine attacks, but this trend was observed only in the MO group." (PMID 29922128, 2018). "HCRT-1 concentration in MA, MO, both migraine patients (MA, MO) and control subjects regarding different genotypes of 5-HTTLPR, HCRTR1 G1222A and *G29A." (PMID 29922128, 2018). "According to our preliminary study, performed on a group of 34 migraine patients, both 5-HTTLPR and HCRTR1 G1222A polymorphisms may be associated with 5-HT and HCRT-1 concentrations." (PMID 29922128, 2018). "We also correlated 5-HT and HCRT-1 concentrations with the clinical features of migraine." (PMID 29922128, 2018). "Taken together, evidences indicated the significant role of 5-HT and HCRT in migraine." (PMID 29922128, 2018). "5-HT and HCRT-1 concentration in MA, MO, both migraine patients (MA+MO) and controls." (PMID 29922128, 2018). "Although, plasma HCRT-1 concentration did not correlate with the duration of migraine history and attack frequency, both in MA and MO patients." (PMID 29922128, 2018). "Further, the fact that dual HCRT antagonists frequently produce headache (although not migraine or CH-like pain) as a side effect have provided indirect evidence that hypofunction of HCRT signaling may destabilize trigeminal nociceptive processing resulting in headache." (PMID 26289164, 2015).
Cognitive impairment (8 papers, 2014 to 2025). Abnormal cognition is characterized by deficits in thinking, reasoning, or remembering. "In Y‐maze test, icv.HCRT‐1 and CUMS rats demonstrated cognitive impairment, as indicated by a significant decrease in the proportion of time spent exploring the new arm compared to the CTR group." (PMID 39119889, 2024).
schizophrenia (7 papers, 2016 to 2026). A major psychotic disorder characterized by abnormalities in the perception or expression of reality. "There was a significant decrease in the amount of HCRT-1 in the hypothalamus in women with schizophrenia." (PMID 39796111, 2024). "Postmortem studies of Hcrt-1 immunoreactivity in the hypothalamus, HCRT-1 levels in cerebrospinal fluid, and the expression of the mRNA receptor of HCRTR hypocretin in the superior frontal gyrus in patients with schizophrenia also showed some differences vs. the control group." (PMID 39796111, 2024).